ME3 (malic enzyme 3)
Description:
Catalyzes the oxidative decarboxylation of (S)-malate to pyruvate using NADP(+), and is able to reverse the reaction but only with significantly lower efficiency. Can also catalyze the decarboxylation of oxaloacetate into pyruvate (By similarity).
Synonyms: NADP-ME
Tractability: Small molecule: a structure with a bound ligand is known. PROTAC: ubiquitination databases record sites on it; its protein half-life has been measured; a small molecule that binds it is known.
Target class: Enzyme; Oxidoreductase
Gene: Protein-coding gene on chromosome 11 (86,438,751 to 86,672,636, reverse strand). Ensembl gene ENSG00000151376.
Subcellular location: Mitochondrion matrix
Pathways (Reactome):
Metabolism: Pyruvate metabolism
Gene Ontology:
Molecular function: malate dehydrogenase (decarboxylating) (NADP+) activity; malic enzyme activity; NADP+ binding; NAD binding; NADP binding; oxaloacetate decarboxylase activity; oxidoreductase activity, acting on the CH-OH group of donors, NAD or NADP as acceptor
Biological process: malate metabolic process; pyruvate biosynthetic process
Cellular component: mitochondrion; mitochondrial matrix
Genetic constraint (gnomAD): Loss-of-function variants: 41 observed, 62.36 expected, observed/expected ratio (o/e) 0.66, 90% interval 0.51 to 0.85. The upper end of that interval is the gene's LOEUF score, 0.85, which puts it in group 3 of 6, group 1 being the genes least tolerant of losing a copy. Missense variants: 629 observed, 761.36 expected, observed/expected ratio (o/e) 0.83, 90% interval 0.77 to 0.88. Synonymous variants: 298 observed, 304.93 expected, observed/expected ratio (o/e) 0.98, 90% interval 0.89 to 1.08.
Homologues: Orthologues: chimpanzee ME3 (99% identical), macaque ME3 (99% identical), dog ME3 (96% identical), guinea pig ME3 (95% identical), pig ME3 (95% identical), mouse Me3 (94% identical), rat Me3 (94% identical), rabbit ME3 (90% identical), zebrafish me3 (76% identical), tropical clawed frog me3 (74% identical), Caenorhabditis elegans men-1 (52% identical), Drosophila melanogaster Men-b (51% identical), and 4 more. Paralogues in human: ME1 (67% identical), ME2 (52% identical).
Diseases named in the same sentence as ME3 in open-access papers:
ME3 is named in the same sentence as 20 diseases in open-access papers, as found by Europe PMC text mining. Sharing a sentence is not in itself a finding about the gene and the disease. The quoted sentences say what the papers report.
breast carcinoma (4 papers, 2017 to 2024). "The study suggests that using ME3 as a predictive tool could help identify breast cancer patients who are likely to respond positively to NET." (PMID 38254828, 2024). "This suggests that TP53AIP1 and ME3 may function as tumor suppressors, and MRPL13 might act as an oncogene in breast cancer." (PMID 38310106, 2024).
pancreatic cancer (2 papers, 2020 to 2022). "In pancreatic cancer, ME3 promotes proliferation, epithelial to mesenchymal transition, and aggressiveness." (PMID 33375130, 2020). "Highly specific inhibitors of ME3 could provide an effective therapy across a number of cancer patients, and ME3 was proven to be found in pancreatic cancer, which is a gastrointestinal tumor." (PMID 36213507, 2022). "Interestingly, ME3 has been recently reported as contributing to proliferation and aggressiveness in pancreatic cancer via its impact on energy production." (PMID 33375130, 2020). "Noteworthy, in pancreatic cancer, ME3 expression has been recently found higher in tumors than that in non-tumor tissues, and patients with higher ME3 levels had significantly shorter survival than those with lower levels according to the Badea and The Cancer Genome Atlas (TCGA) databases." (PMID 33375130, 2020).
colorectal cancer (1 paper, 2020). A primary or metastatic malignant neoplasm that affects the colon or rectum. "Loss of NAT2, a non-essential enzyme involved in drug metabolism, in colorectal cancers emerged as an attractive target conceptually different from synthetic lethality (ENO2, PRMT5, ME3) or targeting genes essential for cell survival (POLR2A, RPA70, or PSMC2)." (PMID 32161261, 2020).
preeclampsia (1 paper, 2024). Preeclampsia is a hypertensive disorder of pregnancy that is characterized by new-onset hypertension with proteinuria presenting after 20 weeks of gestation, and depending on mild or severe forms may initially present with severe headache, visual disturbances, and hyperreflexia. "Because these genes' causal direction was from preeclampsia to ME3, the conclusion was that inflammation was the result, but not the cause, of this disease." (PMID 38666214, 2024). "Meanwhile, CACNA1S was the top gene mediating the causal direction from ME3 to preeclampsia." (PMID 38666214, 2024). "Moreover, within ME3, diffwgcna further found that 415 of its 516 genes were significantly hypomethylated in preeclampsia samples, which was also achieved via limma regression." (PMID 38666214, 2024).
prostate carcinoma (1 paper, 2025). A carcinoma that arises from epithelial cells of the prostate gland. "By contrast, in prostate cancer cells, MALAT1 silencing downregulates ME3, PDK1, PDK3, and choline kinase—enzymes critical for OXPHOS." (PMID 41199749, 2025).
schizophrenia (1 paper, 2024). A major psychotic disorder characterized by abnormalities in the perception or expression of reality. "A recent study involving protein network analysis in ME3 showed the involvement of WDFY1 protein in a mouse model of schizophrenia." (PMID 37971544, 2024).
Sepsis (1 paper, 2025). Sepsis is defined as life-threatening organ dysfunction caused by a dysregulated host response to infection. "For instance, gene module ME1 was downregulated, while ME2, ME3 and ME4 were upregulated in sepsis samples compared to healthy controls." (PMID 40965975, 2025).
cancer (9 papers, 2017 to 2023). A tumor composed of atypical neoplastic, often pleomorphic cells that invade other tissues. "Analysis of the eligible samples revealed that recurrent patients show high values for all the variables associated with the severity of cancer and exhibit high expression levels for ME3, PDK3, CHKA, and MALAT1 transcripts." (PMID 33375130, 2020). "We found that most cancer cell lines express higher levels of ME1 than of ME2 and ME3, although some cell lines predominantly expressed ME2 and ME3." (PMID 28481367, 2017). "Because WA predominantly increased DNA methylation, we mainly focused on verification of hypermethylation effects obtained for selected genes related to cancer invasiveness (ADAM8, PLAU, and TNFSF12), detoxification (GSTM1) or mitochondrial functions (ME3), in relation to gene expression silencing." (PMID 28467815, 2017).
tumor (8 papers, 2016 to 2025). "Concerning the 8 MRGs expression pattern, 4 genes, namely ACSL1, ALDH2, TP53AIP1, and ME3, were observed to be downregulated in tumor tissues while being upregulated in adjacent-normal tissues." (PMID 38310106, 2024). "In pancreatic cancer, for example, malic enzyme 2 (ME2) is frequently co-deleted along with the SMAD4 tumor suppressor, rendering tumor cells dependent on the only remaining mitochondrial malic enzyme isoform, ME3." (PMID 33540663, 2021). "They reported that depleting ME3 selectively killed ME2-null PDAC cells, and so hypothesised potential new specific targets for novel inhibitors in SMAD4-mutated tumours." (PMID 29329208, 2018). "Malic enzyme’s isoforms ME2 and ME3 reside in mitochondria whereas ME1 is cytosolic, and all of them are frequently overexpressed in tumor tissues of diverse origin." (PMID 26869992, 2016).
infection (3 papers, 2019 to 2024). The state of being infected such as from the introduction of a foreign agent such as serum, vaccine, antigenic substance or organism. "In the same experiment, we also tested the recruitment of H3K9me1, me2, and me3 and observed that all three H3 marks are associated with the KSHV genome within 24 hr of de novo infection." (PMID 31682228, 2019).
ME3 also shares sentences with these, for which no sentence is quoted: acute myeloid leukemia (1 paper); Airway obstruction (1); co-infection (1); diabetes (1); gastrointestinal tumor (1); Hepatic steatosis (1); Huntington disease (1); melanoma (1); pancreatic adenocarcinoma (1); pancreatic ductal adenocarcinoma (1).